OR51C1 (olfactory receptor family 51 subfamily C member 1)
Description:
Odorant receptor.
Synonyms: OR51C1P; OR51C3P; OST734; OR51C2P
Gene: Protein-coding gene on chromosome 11 (4,690,423 to 4,697,853, reverse strand). Ensembl gene ENSG00000197674.
Subcellular location: Membrane
Gene Ontology:
Molecular function: olfactory receptor activity; G protein-coupled receptor activity; signaling receptor activity
Biological process: cellular response to lipid; detection of chemical stimulus involved in sensory perception of smell; G protein-coupled receptor signaling pathway; system process
Cellular component: plasma membrane; membrane
Homologues: Orthologues: dog OR51C1 (86% identical), rabbit OR51C1 (86% identical), mouse Or51f23b (83% identical), pig OR51C1 (79% identical). Paralogues in human: OR51F2 (59% identical), OR51G2 (53% identical), OR51G1 (53% identical), OR51I2 (52% identical), OR51T1 (50% identical), OR52K1 (50% identical), OR51A4 (50% identical), OR51L1 (49% identical), OR51M1 (49% identical), OR52K2 (49% identical), OR51A7 (49% identical), OR51E2 (49% identical), and 39 more.